ELP5 (elongator acetyltransferase complex subunit 5)
Description:
Component of the elongator complex which is required for multiple tRNA modifications, including mcm5U (5-methoxycarbonylmethyl uridine), mcm5s2U (5-methoxycarbonylmethyl-2-thiouridine), and ncm5U (5-carbamoylmethyl uridine). The elongator complex catalyzes formation of carboxymethyluridine in the wobble base at position 34 in tRNAs. Involved in cell migration (By similarity).
Synonyms: C17orf81; DERP6; HSPC002; MSTP071; MST071
Tractability: PROTAC: ubiquitination databases record sites on it; its protein half-life has been measured.
Gene: Protein-coding gene on chromosome 17 (7,250,823 to 7,260,165, forward strand). Ensembl gene ENSG00000170291.
Subcellular location: Nucleus; Cytoplasm
Subcellular location (Human Protein Atlas): Nucleoplasm; Cytosol
Pathways (Reactome):
Chromatin organization: HATs acetylate histones
Gene Ontology:
Molecular function: protein binding; tRNA binding
Biological process: positive regulation of cell migration; regulation of translation; tRNA modification; tRNA wobble uridine modification
Cellular component: cytoplasm; cytosol; elongator holoenzyme complex; nucleoplasm; nucleus
Genetic constraint (gnomAD): Loss-of-function variants: 35 observed, 34.91 expected, observed/expected ratio (o/e) 1, 90% interval 0.76 to 1.33. The upper end of that interval is the gene's LOEUF score, 1.33, which puts it in group 5 of 6, group 1 being the genes least tolerant of losing a copy. Missense variants: 373 observed, 390.62 expected, observed/expected ratio (o/e) 0.95, 90% interval 0.88 to 1.04. Synonymous variants: 161 observed, 154.49 expected, observed/expected ratio (o/e) 1.04, 90% interval 0.92 to 1.19.
Homologues: Orthologues: chimpanzee C17orf81 (99% identical), macaque ELP5 (97% identical), pig ELP5 (83% identical), rabbit ELP5 (82% identical), dog ELP5 (82% identical), guinea pig ELP5 (78% identical), mouse Elp5 (75% identical), rat Elp5 (75% identical), tropical clawed frog elp5 (34% identical), zebrafish elp5 (34% identical).
Diseases named in the same sentence as ELP5 in open-access papers:
ELP5 is named in the same sentence as 8 diseases in open-access papers, as found by Europe PMC text mining. Sharing a sentence is not in itself a finding about the gene and the disease. The quoted sentences say what the papers report.
gallbladder cancer (5 papers, 2019 to 2026). "On the basis of the results of this study, low ELP5 expression following gemcitabine treatment may be associated with poor survival in patients with gallbladder cancer." (PMID 35715750, 2022). "In gallbladder cancer, patients with low expression of Elp5 respond poorly to gemcitabine treatment." (PMID 41501031, 2026). "In gallbladder cancer, patients with low expression of Elp5 have poor response to gemcitabine treatment." (PMID 41501031, 2026). "Loss of ELP5 and ELP1 has been demonstrated to directly impede the wobble U34 tRNA modification leading to cancer of the gallbladder and medulloblastoma respectively." (PMID 36448458, 2023). "In a study on gallbladder cancer, the role of elongator complex subunit 5 (ELP5) in gemcitabine sensitivity was identified using the genome-wide CRISPR/Cas9 screen." (PMID 35715750, 2022). "They identified ELP5 (elongator acetyltransferase complex subunit 5) in gallbladder cancer." (PMID 38084101, 2023).
ischemic stroke (1 paper, 2025). A stroke disorder caused by obstruction of blood flow to the brain, due to thrombotic (local blood clot formation) or embolic (due to a blood clot or other material traveling from another site) event. "In ischemic stroke, we found that MPO, CALCRL, PPP5C, KTN1-AS1, CCR1, CTB-50L17.9, CCR9, ZNF362, ZIK1, ELP5, CKAP2, NUP88, and SEC16A show risk effects (OR > 1)." (PMID 40624693, 2025). "Notably, ELP5 showed inconsistent causal effect directions between the MR and FUSION analyses for ischemic stroke." (PMID 40624693, 2025).
melanoma (1 paper, 2018). A malignant, usually aggressive tumor composed of atypical, neoplastic melanocytes. "In a previous study the migration and tumorigenicity of melanoma-derived cells was shown to be significantly decreased upon depletion of ELP1, ELP3, ELP5 or ELP6 in melanoma cells." (PMID 30597914, 2018).
tumor (3 papers, 2019 to 2021). "Tissue microarray contains GBC tumour tissues was used to evaluate the association between the expression of ELP5, DNMT3A and PAX5." (PMID 34823564, 2021). "RT-qPCR, MS-qPCR and ChIP-qPCR were used to evaluate the direct association between ELP5 transcription and DNA methylation in tumour and non-tumour tissues of GBC." (PMID 34823564, 2021). "The Elongator complex subunit 5 (ELP5) has been identified as a pivotal tumor suppressor to induce gemcitabine-associated cytotoxic effects in GBC cells." (PMID 31792210, 2019). "The results showed that ELP5 was drastically downregulated at the mRNA level in tumour tissues in comparison with adjacent normal tissue counterparts in 87.5% of the GBC samples." (PMID 34823564, 2021). "Next, we used methylation-specific quantitative PCR (MS-qPCR) to evaluate the relative methylation level of the ELP5 promoter in 40 GBC tumour tissues." (PMID 34823564, 2021). "Although we have uncovered that ELP5 acts as a tumour suppressor affecting gemcitabine therapeutic responses and survival outcomes in GBC patients, the mechanism inducing ELP5 repression in GBC patients remains unclear." (PMID 34823564, 2021). "ELP5 expression in xenograft tumours was significantly induced under DAC pre-treatment." (PMID 34823564, 2021). "To clarify the expression status of ELP5 in GBC tissues, we detected ELP5 mRNA level in 40 GBC tumour tissues and paired adjacent normal tissues." (PMID 34823564, 2021).
cancer (2 papers, 2019 to 2021). A tumor composed of atypical neoplastic, often pleomorphic cells that invade other tissues. "Expression of ELP4 and ELP5 at mRNA level is associated with increased sensitivity to olaparib in GDSC pan-cancer cell lines." (PMID 33803939, 2021). "While ELP4 and ELP5 mRNA expression are associated with olaparib sensitivity from univariate analysis of GDSC pan-cancer cell lines, ELP4 and ELP6 missense variants may contribute to sensitivity to olaparib in the HGSOC cell line TOV2978G." (PMID 33803939, 2021).
ELP5 also shares sentences with these, for which no sentence is quoted: bile duct cancer (1 paper); Obesity (1); type 2 diabetes (1).